IL9 (interleukin 9)
Diseases named in the same sentence as IL9 in open-access papers (continued):
Sharing a sentence is not in itself a finding about the gene and the disease.
dilatation (1 paper, 2022). "Collectively, these results are consistent in showing that the combined cardiac overexpression of IL9, IL3, IL4, IL13, and IL15 during the chronic phase of CVB3-induced VM can significantly improve the outcome of cardiac disease, reducing cardiac dilatation and dysfunction." (PMID 35508525, 2022).
disc degeneration (1 paper, 2023). "IL-9 was shown to upregulate TNF-α and PGE2 production in NP cells, and its blood levels were positively associated with the degree of disc degeneration in IDD patients." (PMID 37101594, 2023).
disseminated candidiasis (1 paper, 2019). Systemic candidiasis occurs when Candida yeast enters the bloodstream and may spread (becoming disseminated candidiasis) to other organs, including the central nervous system, kidneys, liver, bones, muscles, joints, spleen, or eyes. "IL-9 is a pro-inflammatory cytokine derived from Th-9 cells that was consistently elevated based on our intracellular flow data and on day 4 PI in serum from infected Nos3-/- mice, suggesting it contributes to protection against disseminated candidiasis." (PMID 31671151, 2019).
egg allergy (1 paper, 2016). A food allergy that is an allergy or hypersensitivity to dietary substances from the yolk or whites of eggs, causing an overreaction of the immune system which may lead to severe physical symptoms. "Using a combination of differential gene expression and multiplex cytokine measurement, we observed that egg allergy was associated with IL-9, IL-5, and TNFα expression and secretion, as well as expression of CEACAM1, and CISH." (PMID 27788149, 2016).
empyema (1 paper, 2021). An accumulation of pus in a body cavity, usually the pleural space. "The diagnostic accuracy of CD4+IL-9+, CD4+IL-17+, CD4+IL-22+, CD4+CD25+FOXP3+ T cells, and ADA in the differentiation of tuberculous from non-tuberculous effusions (malignant, empyema, and parapneumonic effusions)." (PMID 34925358, 2021).
eosinophilic diseases (1 paper, 2024). "Moreover, it is a fact that the expression of biologically active IL-9 by human eosinophils implies their potential role in influencing the recruitment and activation of cells associated with the pathogenesis of various eosinophilic diseases." (PMID 38337546, 2024).
epidermolysis bullosa acquisita (1 paper, 2023). "Serum IL-9 levels were not elevated in epidermolysis bullosa acquisita, another sAIBD." (PMID 37398641, 2023).
epilepsy (1 paper, 2024). A brain disorder characterized by episodes of abnormally increased neuronal discharge resulting in transient episodes of sensory or motor neurological dysfunction, or psychic dysfunction. "Elevated levels of IL‐1β, IL‐6, IL‐9, and TNF‐α have been linked to the subsequent onset of epilepsy in children who experienced acute seizures." (PMID 38361811, 2024).
fibrosarcoma (1 paper, 2022). A malignant mesenchymal fibroblastic neoplasm affecting the soft tissue and bone. "We also investigated whether IL-9 affects anti-tumor therapeutic effects in vivo in the MCA205 fibrosarcoma model and we found indeed that neutralization of IL-9 with anti-IL-9 antibody abolished the anti-tumor therapeutic effects of E2f8-knockdown Th9 cells." (PMID 36241625, 2022).
G6PD deficiency (1 paper, 2023). An X-linked genetic condition caused by alterations in the gene G6PD that result in moderately to severely decreased activity levels of the enzyme glucose-6-phosphate dehydrogenase. "G6PD deficiency has been associated with a proinflammatory state with over-expression of IL-8, IL-4, IL-5, and IL-9 cytokines, and increased chemotaxis of eosinophils and Th2 immune polarization." (PMID 37753082, 2023).
gallbladder polyp (1 paper, 2024). "We identified a credible correlation between circulating interleukin-9 (IL-9) levels and gallbladder polyp risk in univariable MR analysis (IVW—OR: 0.523, 95%CI: 0.345–0.794, p = 0.0007; WM—OR: 0.552, 95%CI: 0.327–0.932, p = 0.026; MR Egger—OR: 0.470, 95%CI: 0.152–1.456, p = 0.252)." (PMID 39439893, 2024). "Additionally, two animal studies offered insights into the relationship between IL-9 and gallbladder polyps." (PMID 39439893, 2024). "However, observational evidence on IL-9 and gallbladder polyp even biliary intraepithelial neoplasia was limited to date." (PMID 39439893, 2024). "Additionally, we discovered inverse correlations between IL-9 and gallbladder polyp." (PMID 39439893, 2024).
gastrointestinal allergies (1 paper, 2019). "Studies with IL-9 overexpressing mice revealed that IL-9 also plays role in gastrointestinal allergies." (PMID 31035677, 2019).
H1N1) virus infection (1 paper, 2010). "In our critically ill patients with nvA(H1N1) virus infection we found increased levels of some cytokines: IP-10, TNFα, IL-15, IL-12, IL-6, IL-8 and IL-9." (PMID 21062445, 2010).
Headache (1 paper, 2018). Cephalgia, or pain sensed in various parts of the head, not confined to the area of distribution of any nerve. "Zika virus-infected subjects who reported headaches showed higher plasma levels of TNF-α, IL-17A, IL-2, IL-9, IL-12p70, MIP-1α, G-CSF, GM-CSF, and VEGF, and significantly higher levels of IL-5 (p = 0.0015) compared to those without headache." (PMID 29774022, 2018).
Hepatitis (1 paper, 2021). Inflammation of the liver. "Thus, IL-35 not only eliminated the function of CD8+ T cells in a direct way, but also reduced IL-9 production by CD4+ T cells, and in turn, would lead to a suppression in CD8+ T cell-mediated cytotoxicity in hepatitis and HCC patients." (PMID 34177894, 2021).
hepatitis B- (1 paper, 2021). "IL-9 expression in the serum was also significantly decreased in hepatitis B-related HCC patients compared with in CHB patients (P=0.025, SNK-q test)." (PMID 34177894, 2021). "The aim of present study was to investigate the modulatory role of interleukin (IL)-35, an immunosuppressive cytokine, to IL-9-secreting T cells in hepatitis B-related HCC." (PMID 34177894, 2021). "However, IL-9 production was notably reduced by peripheral HBV-specific Th9 cells in hepatitis B-related HCC patients compared with in CHB patients (P=0.027, SNK-q test)." (PMID 34177894, 2021). "We firstly screened the IL-35 and IL-9 level in the serum in hepatitis B-related HCC patients." (PMID 34177894, 2021). "Increased IL-9 and decreased IL-35 level in hepatitis B-related HCC patients post therapy might partly reflect the restoration of effort T cell function." (PMID 34177894, 2021). "Administration of anti-IL-9 neutralization antibody blocked Th9-induced CD8+ T cells cytotoxicity in both CHB and hepatitis B-related HCC patients (P<0.05, SNK-q tests)." (PMID 34177894, 2021). "Serum IL-9 level was notably reduced in both CHB patients (103.8 ± 12.95 pg/mL), and hepatitis B-related HCC patients (95.27 ± 12.53 pg/mL) compared with in NC (134.6 ± 6.49 pg/mL) (P<0.0001, SNK-q tests)." (PMID 34177894, 2021). "Thus, down-regulation of HBV-specific Th9 cells and IL-9 secretion might be insufficient for maintaining CD8+ T cells, leading to HBV-specific CD8+ T cell dysfunction or exhaustion during chronic HBV infection, especially in hepatitis B-related HCC." (PMID 34177894, 2021). "In line with previous report, our current results suggested a decreased serum IL-9 and circulating non-specific and HBV-specific Th9 cells, but not Tc9 cells, in CHB and hepatitis B-related HCC." (PMID 34177894, 2021). "Peripheral CD8+ T cells from six NC, thirteen CHB, and ten hepatitis B-related HCC patients were co-cultured with HepG2.2.15 cells in the presence or absence of autologous Th9 cells and anti-IL-9 neutralization antibody." (PMID 34177894, 2021).
hip fracture (1 paper, 2022). Traumatic or pathological injury to the hip in which the continuity of either the femoral head, femoral neck, intertrochanteric or subtrochanteric regions is broken. "Unsurprisingly, our study also observed significantly increased levels the Th1 (combination of IL-2, IFN-γ and IL-12) and T cell growth and activation factors (a combination of IL-4, IL-7, IL-9, IL-12, IL-15, GM-CSF) in the delirious hip fracture patients compared to the non-delirious group." (PMID 35641947, 2022).
hyper-IgE syndrome (1 paper, 2017). A condition that is characterized by elevated serum IgE, dermatitis, and respiratory infections. "However in patients with hyper IgE syndrome (HIES) caused by STAT3 mutation, this IL-9 response was significantly lower in the presence of IL-4, which could be due to the deficiency of Th17 cell subset in these patients." (PMID 29371571, 2017).
hyperandrogenism (1 paper, 2022). Excessive secretion of androgens from the adrenal glands or gonads. "And there is a randomized controlled trial using BNZ-1, a selective and simultaneous inhibitor of cytokines IL-2, IL-9, and IL-15, for the treatment of hyperandrogen-induced hair loss.It shows that factors that inhibit IL-15 such as BNZ-1 have a role in the treatment of PCOS hyperandrogenism." (PMID 35250857, 2022).
hyperreactivity (1 paper, 2022). "The IL-9 level, which evaluates bronchial hyperreactivity, was also insignificantly elevated in the Poractant α group." (PMID 35372166, 2022).
hypothyroidism (1 paper, 2023). Abnormally low levels of thyroid hormone. "Conversely, when we treated hypothyroidism as an exposure factor, we detected a causal association between hypothyroidism and 13 inflammatory cytokines (IL-13, IL-16, IL-2rα, IL-6, IL-7, IL-9, G-CSF, SCGF-β, IP-10, MIG, MIP-1β, SDF-1α, and TNF-α)." (PMID 38317717, 2023).
infectious mononucleosis (1 paper, 2023). A condition characterized by an increase in mononuclear white blood cells and swollen lymph nodes, which is usually caused by infection with the Epstein-Barr virus. "However, the role of the AREG/EGFR/HIF-1α pathway in regulating interleukin-9 (IL-9) production by T cells in adult patients with infectious mononucleosis (IM) has not been fully elucidated." (PMID 36154925, 2023).
Insulin resistance (1 paper, 2025). Increased resistance towards insulin, that is, diminished effectiveness of insulin in reducing blood glucose levels. "Given the established role of adipose tissue inflammation in the pathogenesis of insulin resistance and the emerging role of immune cell types in mediating metabolic homeostasis, we investigated the role of the IL-9 signaling pathway in adipose tissue inflammation." (PMID 40962954, 2025).
ischemia (1 paper, 2023). A hypoperfusion of the BLOOD through an organ or tissue caused by a PATHOLOGIC CONSTRICTION or obstruction of its BLOOD VESSELS, or an absence of BLOOD CIRCULATION. "Furthermore, Il9, Gpx5, and Gpx6 were completely disconnected from the main gene cluster in the ischemia+Placebo network." (PMID 37426668, 2023).
ischemic cardiomyopathies (1 paper, 2013). "Increased plasma IL-9 has been reported in patients with ischemic and non-ischemic cardiomyopathies, inversely correlated with parameters of impaired left ventricular function, and increased serum IL-9 has also been reported in 45 patients with acute ischemic stroke of different etiology." (PMID 24023645, 2013).
kidney (1 paper, 2023). "We compared markers of kidney inflammation and injury (neutrophil gelatinase-associated lipocalin, kidney injury molecule-1) as well as plasma and urine levels of T cell-associated cytokines (TNF-α, interferon-γ, interleukin (IL)-2, IL-4, IL-6, IL-8, IL-9, and IL-10) between groups." (PMID 36938084, 2023).
liver carcinoma (1 paper, 2021). An epithelial or non-epithelial malignant neoplasm that arises from the liver. "Compared to the T1 subtype, T9 CAR-T cells preferentially secrete IL-9, which displays anti-tumoral effects on both hematologic (ALL) and solid (liver carcinoma) tumors." (PMID 34944921, 2021).
mastitis (1 paper, 2020). Inflammation of breast tissue during lactation or postpartum due to an obstructed duct or infection. "In this regard, we have also identified IL9 as a key gene associated with S. aureus-induced subclinical mastitis." (PMID 32944235, 2020). "Five genes (EPOR, IL9, IFNL3, CCL26, and IL26) that were involved in this pathway might serve as potential molecular markers for breeding programs that enhance resistance to S. aureus infection and mastitis." (PMID 32944235, 2020).
meningioma (1 paper, 2023). A generally slow growing tumor attached to the dura mater. "In contrast, our study found that elevated levels of IL-9 in peripheral blood are associated with a decreased risk of developing meningiomas." (PMID 37425011, 2023). "Based on the results of our MR analysis, which examines 41 cytokines in the largest GWAS datasets available, we were able to draw the relatively more reliable conclusion that elevated levels of circulating TNF-β, CXCL1, and lower levels of IL-9 were associated with a high risk of meningioma." (PMID 37425011, 2023). "Moreover, we found that higher interleukin-9 (IL-9) levels can reduce meningioma risk (OR = 0.544, 95% CI = 0.322–0.918) using IVW methods." (PMID 37425011, 2023). "The role of IL-9 in meningiomas requires further investigation." (PMID 37425011, 2023). "However, the specific mechanisms of IL-9 in meningiomas require further investigation." (PMID 37425011, 2023).
metastatic melanoma (1 paper, 2019). A melanoma that has spread from its primary site to another anatomic site. "However, a loss of IL-9-producing T cells was described in patients with metastatic melanoma." (PMID 30984190, 2019).
Miscarriage (1 paper, 2021). A pregnancy that ends at a stage in which the fetus is incapable of surviving on its own, defined as the spontaneous loss of a fetus before the 22th week of pregnancy. "Il-9 reaches the highest concentrations of all cytokines and chemokines both in pregnant and non-pregnant uterus and additionally in the placenta, but there are no reports of values that may be achieved in the serum of women with miscarriage." (PMID 34444287, 2021).
MRSA pneumonia (1 paper, 2024). "In children with MRSA pneumonia, miR-155 has been associated with a Th9/IL-9 response, and targeting of miR-155 was suggested to be a potential new strategy to treat MRSA." (PMID 37982695, 2024).
myelofibrosis (1 paper, 2025). A partial or complete replacement of the bone marrow stroma by fibrous tissue. "We identified a set of inflammatory cytokines, including IL-1alpha, IL-4, IL-6, IL-7, IL-9, IL-15 and TNF-alpha, which are elevated in the serum of JAK2V617F mice, similar to the alterations in circulating cytokines observed in patients with myelofibrosis." (PMID 40386398, 2025).
Nasal polyposis (1 paper, 2020). Polypoidal masses arising mainly from the mucous membranes of the nose and paranasal sinuses. "Indeed, the effect of IL-4/IL-13 and IL-5 on nasal epithelial repair was already showed but to date, no study has precisely described the role of IL-6, IL-9 and IL-10 (new ILs described in nasal polyposis) on human nasal epithelial cells in an in vitro wound repair model." (PMID 32209102, 2020).
nephrotic syndrome (1 paper, 2025). A collection of symptoms that include severe edema, proteinuria, and hypoalbuminemia; it is indicative of renal dysfunction. "IL-9, also released by T cells, seems to act antagonistically to IL-7 on the podocyte in nephrotic syndrome pathogenesis." (PMID 39946431, 2025).
pancreatitis (1 paper, 2025). Inflammation of the pancreas. "However, current research on the role of IL-9 in pancreatitis is still insufficient, and more studies are needed to further explore and validate the specific mechanisms of IL-9’s action." (PMID 39958351, 2025).
papillary thyroid carcinoma (1 paper, 2022). "Studies have confirmed that in patients with papillary thyroid carcinoma combined with HT, IL-9 secreted by Th9 cells was abnormally higher than that in patients without HT." (PMID 35935994, 2022).
peripheral T cell lymphoma (1 paper, 2023). "Although IL-9 was sporadically detectable in EBV positive non-nasal peripheral T cell lymphoma, expression of IL-9 mRNA was strongly elevated in nasal natural killer T-cell lymphoma cell lines and patients, which is closely associated with EBV infection." (PMID 36154925, 2023).
plasmacytoma (1 paper, 2014). Plasmacytoma is a localized mass of neoplastic monoclonal plasma cells that represents approximately 5% of all plasma cell neoplasms. "In vivo, nucleophosmin-ALK expression during transgenic IL-9 expression led to the development of murine plasmacytoma, plasmoblastic/anaplastic lymphoma and precursor T-lymphoblastic lymphoma." (PMID 24722378, 2014).
Pneumocystis infection (1 paper, 2018). "In the present study, we provided insights into the function of IL-9 during clearance of Pneumocystis and explore the effect of IL-9 on Th17 responses in Pneumocystis infection using the IL-9 deficient (IL-9−/−) mice." (PMID 29887863, 2018). "Using IL-9-deficient (IL-9−/−) mice, flow cytometry, real-time PCR and enzyme-linked immunosorbent assay (ELISA) were conducted to investigate the immune function related to Th17 response in defense against Pneumocystis infection." (PMID 29887863, 2018). "Our presented data demonstrated that IL-9 deficiency could enhance Th17 cells response during Pneumocystis infection." (PMID 29887863, 2018). "Our results suggested IL-9 might be detrimental to controlling Pneumocystis infection and IL-9 deficiency lowered the Pneumocystis burden probably via the increasing Th17 cells." (PMID 29887863, 2018). "Our previous data suggested that IL-9−/− mice recruited more AMs (CD45+F4/80+CD11bintCD11c+) during Pneumocystis infection." (PMID 29887863, 2018). "In our experiments, though two groups presented similar frequencies of Th17 cells expressing IL-23R in BALF by flow cytometry, IL-23R mRNA expression in lung and IL-23 concentration in BALF were elevated in IL-9−/− mice during Pneumocystis infection contrasted with WT mice." (PMID 29887863, 2018). "In our murine model of Pneumocystis infection, PCR results from lung tissue showed upregulated expressions of STAT3 and STAT5 and similar levels of STAT1 expression in IL-9−/− mice compared with WT mice." (PMID 29887863, 2018). "Different from Th2 cells, no studies demonstrate whether Th9 or IL-9 plays a role in the process of Pneumocystis infection till now." (PMID 29887863, 2018).
pregnancy hypertension (1 paper, 2023). "Nevertheless, there is a scarcity of studies investigating the association between IL-9 and pregnancy hypertension." (PMID 38362587, 2023). "We found that GROA and IL-9 exhibited causal relationships with pregnancy hypertension, while interleukin-10 (IL-10) and hepatocyte growth factor (HGF) demonstrated causal relationships with PE." (PMID 38362587, 2023). "Further research is necessary to elucidate the roles of IL-9 in pregnancy hypertension." (PMID 38362587, 2023). "In the positive results, heterogeneity may exist when the exposure is IL-9 and the outcome is pregnancy hypertension, as indicated by the Cochran’s Q statistical analysis of MR Egger and IVW with the P-value less than 0.05." (PMID 38362587, 2023).
Psoriasiform dermatitis (1 paper, 2013). A skin abnormality characterized by redness and irritation, with thick, red skin that displays flaky, silver-white patches (scales). "In addition, IL-9 may induce IL-17- or IL-22 producing γδ T cells in the skin as these cells have been recently reported to play a critical role in IL-23-induced psoriasiform dermatitis in mice." (PMID 23335955, 2013).
pulmonary tuberculosis (1 paper, 2012). A bacterial infection that affects the lungs and is caused by Mycobacterium tuberculosis. "Compared with healthy donors, the peripheral blood plasma of pulmonary tuberculosis patients contained significantly higher levels of IL-6 and IL-9." (PMID 23028695, 2012). "We found that either specific antigen could stimulate PBMCs from pulmonary tuberculosis patients to produce higher levels of IL-6 and IL-9 than PBMCs from HDs." (PMID 23028695, 2012).